U6 (U6 spliceosomal RNA )
Gene: Small nuclear RNA gene on chromosome 2 (88,367,793 to 88,367,862, reverse strand). Ensembl gene ENSG00000283262.
Homologues: Orthologues: chimpanzee U6 (100% identical), rat LOC120094561 (83% identical), dog U6 (73% identical). Paralogues in human: RNU6-338P (86% identical), RNU6-1056P (84% identical), RNU6-1062P (84% identical), RNU6-950P (84% identical), RNU6-1113P (83% identical), RNU6-1151P (83% identical), RNU6-140P (83% identical), RNU6-227P (83% identical), RNU6-24P (83% identical), RNU6-275P (83% identical), RNU6-298P (83% identical), RNU6-39P (83% identical), and 1285 more.